INS (insulin)
Diseases named in the same sentence as INS in open-access papers (continued):
Sharing a sentence is not in itself a finding about the gene and the disease.
Hyperglycemia (continued). "The doses of 35 and 40mg/kg STZ were effective in simulating metabolic characteristics of DM2 in humans.It was confirmed by the presence of polydipsia, hyperglycemia, altered biochemicaltests, insulin resistance and damages to the liver, pancreas, and kidney." (PMID 34431921, 2021). "These comprised measures to hydrate animals (six instances), insulin to prevent severe hyperglycaemia (two instances), and others (24 instances)." (PMID 33669354, 2021). "If hyperglycaemia persists (>10 mmol/l, 180 mg/dL), it is then recommended that insulin treatment should be started." (PMID 34368024, 2021). "Hyperglycemia and hyperinsulinemia are linked with raised levels of plasma PAI-1 levels, and this enlightens eminent quantities of the enzyme in insulin-resistant situations." (PMID 33857223, 2021). "Despite strong recommendations for early insulin administration, how to monitor and treat stress-induced hyperglycemia remains under debate." (PMID 33973089, 2021). "Other mechanisms include β cell dysfunction, sympathetic bursts and hormonal changes which induce hyperglycaemia and impaired tissue responsiveness to insulin." (PMID 33947164, 2021). "The hyperglycemia resulting from these processes is likely to lead to glucose toxicity of β-cells, thereby further decreasing insulin secretory function." (PMID 34220706, 2021). "Recurrent hyperglycaemia visits have been associated with patients <25 years of age, a glucose level >20 mmol/L, being on insulin, and a recent visit to the emergency centre for hyperglycaemia." (PMID 34703733, 2021). "Oxidative stress induced by hyperglycemia can further inhibit the production of insulin by the beta cells of the pancreas." (PMID 33562428, 2021). "PRAS40 mediated mTORC1 inhibition prevents the development of cardiomyopathy, along with improved metabolic function, insulin sensitivity, and reduced systemic hyperglycemia in a diabetic mouse model." (PMID 34440882, 2021). "It is characterized by elevated blood glucose levels (hyperglycemia) due to increased insulin resistance and/or insulin secretion from pancreatic beta (β) cells, which reduces the clearance of blood glucose in peripheral metabolic organs." (PMID 33562070, 2021). "It is characterized by hyperglycemia, a condition with high glucose level in the blood plasma resulting from defects in insulin secretion or its action and in some cases both the impairment in secretion and also action of insulin coexist." (PMID 34429169, 2021). "Intravenous administration of RHI with frequent monitoring and titration of insulin dose is necessary to achieve good glycemic control in critically ill patients with hyperglycemia." (PMID 34071359, 2021). "Hyperglycemia in both patients were initially managed with Intravenous insulin infusion which was adjusted according to hourly blood glucose levels and was later changed to subcutaneous therapy." (PMID 33531061, 2021). "DM is a heterogeneous metabolic disorder characterized by the presence of hyperglycemia due to impairment of insulin secretion, defective insulin action, or both." (PMID 34956773, 2021). "An elevated blood sugar level happens in parallel with insulin resistance, as cells fail to react in a proper manner to insulin, thus leading to hyperglycemia." (PMID 34966477, 2021). "High blood glucose level and low secretion of insulin after administration of -are features of hyperglycemia, and the oral administration of the extracts for 4 weeks significantly reduced the fasting blood glucose level in the diabetic mice." (PMID 34371645, 2021). "Chungkookjang, fermented with B. licheniformis, produces higher contents of γ-PGA during soybean fermentation, and the fermented soybeans improve cognitive dysfunction and hyperglycemia by promoting insulin sensitivity and glucose-stimulated insulin secretion." (PMID 33494481, 2021).
Hyperglycemia (continued). "Long-term hyperglycemia and high-saturated free fatty acids are the key contributors which inhibited insulin secretion, promoted pancreatic β-cell apoptosis, and decrease the number of normal functioning pancreatic β cells." (PMID 34699323, 2021). "Skeletal muscle and liver were the main sites of glucose elimination in the insulin-stimulated state and it was recommended that it be the main tissue responsible forpostprandial hyperglycemia in an insulin resistant subject." (PMID 35540699, 2021). "Others have also shown that reducing insulin is the best strategy for preventing hyperglycaemia, but that consuming extra carbohydrates is the safest option in preventing hypoglycaemia." (PMID 33914197, 2021). "Over time, and with the worsening of the disease, hyperglycemia will establish itself due to the saturation of insulin production, as well as by resistance mechanisms." (PMID 34568974, 2021). "Since kidneys are associated with glucose homeostasis via gluconeogenesis, insulin clearance, and glucose reabsorption, we hypothesized that the increased renal function associated with increased parenchyma may contribute to the induction of hyperglycemia in DEK-DM rats." (PMID 34356489, 2021). "Hyperglycaemia and dyslipidaemia, together with altered insulin signalling, lead to several pathological alterations in neurons, glia and vascular cells, which can lead to nerve dysfunction and ultimately DN." (PMID 33436718, 2021). "Our data support a model that heparin induces hyperglycaemia by inhibiting an insulin‐dependent downstream cascade and glucose uptake in the skeletal muscle." (PMID 34277977, 2021). "Pioglitazone (PIO), of the thiazolidinedione class, is an agonist of peroxisome proliferator-activated receptors (PPARs) and improves hyperglycemia, reduces hyperinsulinemia and enhances β-cell function in a variety of insulin-resistant animal models." (PMID 34358068, 2021). "α cells secrete glucagon in response to hypoglycemia and β cells secrete insulin in response to hyperglycemia." (PMID 35002748, 2021). "Type-2 Diabetes (T2D) is a metabolic disease characterized by hyperglycemia resulting from defects in insulin secretion, insulin action, or both." (PMID 34440882, 2021). "Patients in the incretin-based therapy group had a slightly higher incidence of hyperglycemia-related AEs than the insulin group (57.9% vs 51.2%)." (PMID 34275099, 2021). "The pathophysiology is related to chronic hyperglycemia with impaired metabolism due to insulin secretion dysfunction and/or peripheral tissue insulin resistance." (PMID 34360449, 2021). "Neutral protamine Hagedorn (NPH) insulin is widely used for the treatment of hyperglycemia during hospitalization." (PMID 34075142, 2021). "Resveratrol, a natural polyphenol, has also been shown to normalize hyperglycemia and hyperlipidemia, improve beta-cell function and insulin sensitivity, and lower hepatic glucose production through the activation of SIRT1." (PMID 34656137, 2021). "The decrease in response to insulin leads to increased insulin secretion, which is eventually followed by the failure of pancreatic beta-cells to compensate for the elevated insulin demand, resulting in hyperglycemia." (PMID 33919569, 2021). "Foods derived from plant sources not only provide dietary fiber, promoting glycemic control, but are also sources of phytochemicals such as polyphenols, which decrease hyperglycemia and improve acute insulin secretion and insulin sensitivity." (PMID 34071499, 2021). "The FFAs-induced impairment of insulin sensitivity is observed in normoglycemia as well as in hyperglycemia." (PMID 33320449, 2021). "For insulin dependent diabetic pregnancies after intramuscular betamethasone, hyperglycemia peaks on day-2 and − 3 lasting up to day-5." (PMID 33588801, 2021).
Hyperglycemia (continued). "GCK-MODY is a quasi-experimental human model that allowed to define the respective roles of maternal hyperglycemia and fetal genotype on fetal growth, and to confirm the central role of fetal insulin secretion in fetal growth." (PMID 35069449, 2021). "GDM is defined as hyperglycemia first recognized in pregnancy and can be seen as consequence of an insulin supply inadequate to meet the demands for normal blood glucose regulation." (PMID 34884524, 2021). "Insulin aspart/insulin lispro is preferred over RHI for better PPG control and lower risk of hypoglycemia when managing hyperglycemia in pregnancy with insulin." (PMID 34071359, 2021). "cPLA2 in the VMH plays an important role in AA metabolism to produce prostaglandins and increase insulin sensitivity in skeletal muscles during hyperglycemia in RCD-fed mice." (PMID 33879780, 2021). "In contrast, peripheral organs often demonstrate an increased trend of O-GlcNAcylated proteins which correlates hyperglycemia and contributes to impaired insulin signaling and glucose toxicity." (PMID 33258073, 2021). "Often this will have been because of long-standing hyperglycemia and clinical inertia earlier in their disease, but can erroneously be attributed to insulin." (PMID 34165382, 2021). "We conclude that women with a history of GDM showed alterations in glucose metabolism, including impairments in insulin sensitivity and β-cell function as well as subclinical hyperglycemia already at an early stage of a subsequent pregnancy." (PMID 34682918, 2021). "Reduced insulin sensitivity and impaired glucolipid uptake in obese patients induce hyperglycemia and hyperlipidemia." (PMID 33854556, 2021). "At molecular level, hyperglycemia and insulin mediated HIF1 signaling activation favors the development of hallmarks of cancer with the transforming cell." (PMID 34225729, 2021). "Streptozotocin (STZ) is commonly used for targeting insulin producing beta cells in pancreas to induce hyperglycemia and mimic T2DM disease conditions." (PMID 34166387, 2021). "The administration of relaxins, a family of anti-inflammatory, anti-apoptotic, and anti-fibrotic compounds belonging to the insulin super-family, displayed reduced hyperglycemia-induced damage in the eye and other tissues." (PMID 34281162, 2021). "Studies in SMA experimental model have revealed metabolic defects characterized by fasting hyperglycemia, glucose intolerance, insulin hypersensitivity and hyperglucagonemia." (PMID 34371910, 2021). "•In vitro and in vivo β-cell miR-21 induction reduced glucose-stimulated insulin secretion and led to hyperglycemia." (PMID 34246804, 2021). "Recommendations for management of hyperglycemia-related to alpelisib treatment include commencing insulin-sensitizing oral antidiabetic treatment, such as metformin and pioglitazone, with the option of insulin as rescue medication." (PMID 34281618, 2021). "Oat and buckwheat had been proved to have significant effects on controlling hyperglycemia, insulin response, and diabetic kidney disease." (PMID 35004803, 2021). "On the other hand, new ultra-rapid prandial insulin analogs lead to better postprandial glycemic control reducing hyperglycemia in the early post-prandial phase." (PMID 33755854, 2021). "Type 1 diabetes (T1D) is an autoimmune disease characterized by the disruption of pancreatic beta cells: this leads to a progressive reduction of insulin secretion and subsequent hyperglycemia, along with lipid and protein metabolism derangements." (PMID 33755854, 2021). "Further research is required to investigate the mechanistic relationships among donor hyperglycaemia, insulin therapy and beta cell function in both donors and transplant recipients." (PMID 33665687, 2021). "A patient in this trial had factitious hyperglycemia leading to insulin administration and hypoglycemic coma, which triggered a protocol amendment, highlighting the hazards of such therapy." (PMID 34020705, 2021).
Hyperglycemia (continued). "It would seem that the relationship between insulin therapy and heart function is complex and subtle, with the benefits of insulin therapy during stress hyperglycemia states in myocardial infarction still remaining controversial." (PMID 33463901, 2021). "The glutamine can reduce hyperglycemia by increasing insulin sensitivity and improving its signaling in peripheral tissues which directly stimulate insulin production by the pancreatic beta cells." (PMID 33865313, 2021). "We have found that post-natal growth was altered in babies who required insulin for idiopathic hyperglycemia of prematurity and that SGA neonates were likely resistant to GH and IGF1." (PMID 34447729, 2021). "In various situations, fetal exposure to maternal diabetes has been associated with long-term deleterious effects, particularly defects in glucose-stimulated insulin secretion and hyperglycemia." (PMID 35069449, 2021). "Hyperglycemia with reduced insulin levels was also found in females exposed to diethylhexyl phthalate throughout the gestation/perinatal period." (PMID 34063694, 2021). "It has been amply demonstrated that the “incretin effect” is typically reduced or even absent in people with impaired glucose tolerance or diabetes, and this contributes to defective insulin secretion and hyperglycaemia in patients with type 2 diabetes (T2D)." (PMID 33671882, 2021). "Thirty-two of the participants required insulin to control hyperglycemia, half of them remained diabetic, and six of those continued to use insulin after one year following the surgery." (PMID 34873559, 2021). "Theoretically, initiation of insulin therapy in patients with new onset T1D should not only increase sKlotho concentration by reducing hyperglycemia, but also by down-regulating FGF23 production." (PMID 34603200, 2021). "Hyperglycemia contributed to the environment of hyperinsulinemia and increased the demand of insulin for sugar control, which led to a vicious cycle." (PMID 33661912, 2021). "Hyperfiltration results from the complex interplay of numerous mechanisms and mediators, with a prominent role for hyperglycaemia, distorted insulin levels and angiogenesis." (PMID 33976959, 2021). "Currently, multiple protocols of subcutaneous and intravenous insulin treatments are used to ameliorate hyperglycemia in patients with different diseases during hospitalization." (PMID 34075142, 2021). "The primary goal of the present study is to evaluate the intestinal region-dependent effects of chronic hyperglycaemia and immediate insulin treatment on TNFα expression in myenteric ganglia of different gut segments." (PMID 34572059, 2021). "In general, hyperglycemia weakens the osteogenic and chondrogenic differentiation capability, but interestingly, enhances trans-differentiation into neuron-like cells and insulin-secreting cells." (PMID 33968939, 2021). "Chronic hypersecretion of insulin, however, can lead to a decline in β-cell mass and function and subsequently, to reduced insulin secretion which allows hyperglycemia to manifest." (PMID 33996878, 2021). "A smaller proportion of the participants in the liraglutide group compared with the placebo group who completed treatment at week 52 required insulin rescue (addition of basal insulin, alone or in combination with bolus insulin, to treat hyperglycaemia)." (PMID 33634589, 2021). "Previously, we characterized pancreas-specific PPARγ KO mice that exhibited hyperglycemia and impaired glucose-induced insulin secretion." (PMID 34592314, 2021). "Studies have found that long-term administration of FGF21 to genetically obese mice will ameliorate fasting hyperglycemia via increased glucose uptake and improved hepatic insulin sensitivity." (PMID 33869312, 2021). "(b) Endocrine outcomes, that is, impairment of insulin release and insulin sensitivity, resulting in hyperglycemia." (PMID 34532036, 2021).
Hyperglycemia (continued). "These factors lead to persistent hyperglycemia and subsequently to decreased insulin sensitivity, which in turn can lead to a spectrum of metabolic abnormalities." (PMID 34603052, 2021). "This leads to a state in which the body has become resistant to insulin signaling, with a resulting accumulation of glucose in the circulation, known as hyperglycemia." (PMID 34138882, 2021). "The increased risk of macrosomia in diabetic pregnancy is mainly due to the increased insulin resistance of the mother, which further contributes to maternal hyperglycemia and dyslipidemia." (PMID 33803995, 2021). "As skeletal muscle, the largest organ in the body, is responsible for approximately ∼85% of postprandial glucose uptake, skeletal muscle insulin resistance contributes to the development of hyperglycaemia." (PMID 33387681, 2021). "Efficacy will entail infecting and reprogramming an adequate number of α cells into insulin-producing cells enough to reverse hyperglycemia." (PMID 34882233, 2021). "Type 1 diabetes is a disease with autoimmune features where insulin producing beta cells are progressively lost leading to hyperglycemia and dependence on exogenous insulin." (PMID 34113315, 2021). "STZ damages the insulin-producing β cells of the pancreas, resulting in hypoinsulinaemia and hyperglycaemia." (PMID 34201794, 2021). "Insulin action can be impaired by chronic hyperglycemia, but this defect can be ameliorated by the establishment of euglycemia." (PMID 34912428, 2021). "Inpp4b-deficient animals developed hyperglycemia on normal chow and T2D on HFD due to decreased insulin sensitivity." (PMID 33772116, 2021). "We then exposed neonatal mice cardiomyocytes to 33.3 mM glucose and 100 nM insulin to mimic hyperglycemia and hyperinsulinemia in cardiomyocyte of diabetic heart." (PMID 34604360, 2021). "Glucotoxicity refers to the detrimental effects of chronic exposure to hyperglycemia that can lead to cellular dysfunction and irreversible pancreatic β-cell damage characterized by defective insulin gene expression." (PMID 35052597, 2021). "The expression of visfatin is upregulated by estrogen, inflammation, and hyperglycemia and downregulated by insulin." (PMID 34822574, 2021). "This setting of subjects exhibits an insulin-resistant status characterized by enhanced insulin production but reduced tissue sensitivity to hormone action, and 1-h-post-load hyperglycemia can be regarded as an early marker of IR." (PMID 33613266, 2021). "At 4‐5 years after diagnosis, 93.9% required insulin for management of their hyperglycaemia, 21.2% had hypertension requiring treatment, 28.6% had low‐density lipoprotein ≥130 mg/dL, and 28.6% had high‐density lipoprotein <40 mg/dL." (PMID 33855201, 2021). "Glucocorticoids, in addition to impair insulin secretion, induce hyperglycemia by increasing the synthesis of gluconeogenic enzymes and reducing peripheral tissue-glucose uptake by increasing insulin resistance." (PMID 34417460, 2021). "In hyperglycemia and diabetic conditions, glucose concentration increases in the insulin-independent tissues such as neural tissue, glomeruli, lens, and erythrocytes." (PMID 34663861, 2021). "DM is a metabolic disorder of multiple etiologies characterized by a chronic hyperglycemia with disturbance of carbohydrate, fat, and protein metabolism resulting from issues with insulin secretion, insulin resistance, or both." (PMID 34388207, 2021). "This suggests that insulin potentially exerts beneficial effects against the activation of oxidative stress dependent on sustained hyperglycemia and glycemic variability." (PMID 33740334, 2021). "When the graft-bearing kidney was removed, there was rapid hyperglycemia, indicating that the transplanted islets were the source of insulin in the mice and that the endogenous WT β cells in the recipients had been destroyed." (PMID 34417463, 2021).